IL6 (interleukin 6)
Diseases named in the same sentence as IL6 in open-access papers (continued):
Sharing a sentence is not in itself a finding about the gene and the disease.
Cerebral ischemia (continued). "A recent report has indicated that the proinflammatory cytokine IL-6 contributes to the inflammatory and neurotrophic aspects of cerebral ischemia." (PMID 27010689, 2016). "Some studies have reported that IL-6 aggravates cerebral infarction, whereas other studies have reported the beneficial effects of IL-6 in preventing damaged neuron from undergoing apoptosis and promoting neuronal survival after cerebral ischemia." (PMID 27703487, 2016). "In the acute phase of cerebral ischemia, IL-6 functions as an inflammatory cytokine, while in the subacute and late phases, it contributes to neuroprotection." (PMID 27010689, 2016). "IL-6, apart from its well-known pro-inflammatory function, can also exhibit neurotrophic and regenerative features following cerebral ischemia." (PMID 27829437, 2016). "Elevated levels of interleukin-6 (IL-6) and C-reactive protein (CRP) were found in the systemic circulation of SAH patients, with even higher peaks associated with delayed brain ischemia." (PMID 25110700, 2014). "IL-6 possesses multiple biological functions and has been mainly secreted by astrocyte and microglia during the course of cerebral ischemia/reperfusion." (PMID 23864765, 2013). "For example, activated microglia following cerebral ischemia express a variety of proinflammatory cytokines including interleukin-1β (IL-1β), interleukin-6 (IL-6) and tumor necrosis factor-α (TNF-α), which induce neuroinflammation and neurotoxicity." (PMID 23912236, 2013). "IL-6 can be detected in the brain tissue, cerebrospinal fluid, and serum at reperfusion 2 h after cerebral ischemia." (PMID 23864765, 2013). "In vivo, after cerebral ischemia, IL-1 production contributed to increased IL-6 and CXCL1 since these cytokines were profoundly reduced in the ischemic hemispheres from IL-1α/β double KO mice, although injury-induced cytokine responses were not abolished." (PMID 23024646, 2012). "GW0742 administration i.c.v. dose-dependently inhibited the increase of TNF-α, IL-1β, and IL-6 and the reduction of IL-10 in hippocampus of cerebral ischemia-reperfusion rat." (PMID 23056034, 2012). "The proinflammatory cytokines TNFα, IL-6 and IL-1β have been found in the brain infarct region and the same cytokines have been suggested to be involved in the development of late cerebral ischemia after SAH." (PMID 23259581, 2012). "Rcan1-4 mRNA expression in the same brain ischemia model was determined by real time qRT-PCR, together with the mRNA expression levels of the proinflammatory cytokines IL-1β, TNFα and interleukin 6 (IL-6) and the proinflammatory gene cyclo-oxygenase 2 (Cox-2)." (PMID 22397398, 2012). "IL-6 has a mitogenic effect on astrocytes and induces reactive gliosis in later stages of brain ischemia." (PMID 21450100, 2011). "We have here demonstrated yet another important mechanism involved in cerebral ischemia, neuroinflammation, and we have demonstrated that U0126 blocks enhanced cerebrovascular expression of iNOS, IL-1ß, IL-6 and TNF-α." (PMID 20187933, 2010). "Microglia are activated following in cerebral ischemia and express a variety of proinflammatory cytokines including interleukin -1β (IL-1β), interleukin -6 (IL-6) and tumor necrosis factor -α (TNF-α), which induce in neuroinflammation and neurotoxicity." (PMID 20668522, 2010). "Following cerebral ischemia, immune cells, including microglia, undergo activation, transitioning from the M2 to the M1 phenotype, which leads to the production of pro-inflammatory cytokines such as IL-1β, IL-6, TNF-α, and chemokines." (PMID 40365317, 2025). "While these fold-changes may appear modest, in the context of cerebral ischemia, sustained shifts in the levels of pivotal cytokines like IL-6 are known to significantly influence the inflammatory microenvironment, neuronal function, and recovery trajectories." (PMID 41452851, 2025).
Cerebral ischemia (continued). "Endogenous IL-6 may play a key role in preventing neuronal damage during the acute phase of brain ischemia by activating the signaling protein and STAT3." (PMID 40305179, 2025). "Cerebral ischemia induces astrocytes to release inflammatory factors, such as IL-1, IL-6, and TNF-α, and neurotoxins that may kill matured oligodendrocytes or inhibit the maturation of oligodendrocyte precursor cells." (PMID 38464836, 2024). "Notably, SITG has reduced pro-inflammatory markers NF-κB, TNF-α, and IL-6 in diabetic rats with cerebral ischemia/reperfusion injury." (PMID 39766390, 2024). "It should moreover be noted that the pro-angiogenetic effect of IL-17A may be dependent on the IL-6/STAT3 signaling pathways under EE conditions after cerebral ischemia; this matter should be further explored in the future." (PMID 36873773, 2023). "Tanshinone IIA can reduce the expression of macrophage migration inhibitory factor (MIF) and inflammatory factors (MIF), TNF-α and interleukin (IL)-6 in the brain of rats with cerebral ischemia/reperfusion, thereby alleviating the effects of cerebral ischemia/reperfusion." (PMID 37808475, 2023). "During cerebral ischemia, statins also inhibit the expression of inflammatory cytokines, TNFα and Interleukin-6 (IL-6), in vascular endothelial cells to prevent BBB disruption, and at the site of BBB disruption, they act directly on brain nerve cells to exert their effects." (PMID 36852215, 2023). "Importantly, after geniposide treatment, the expression of IL-6 and iNOS was significantly reduced, which suggested that geniposide exhibited an anti-inflammatory effect after cerebral ischemia." (PMID 37333874, 2023). "CA has demonstrated its importance as an effective inhibitor of 5-lipooxygenase (5-LO) and it has proven its capacity to diminish NF-κB, Interleukin-6 (IL-6), and IL-1β levels during inflammatory processes, especially global cerebral ischemia-reperfusion injuries in rats." (PMID 36359936, 2022). "As opposed to the pro-inflammatory properties of IL-6 in the periphery, central IL-6 may be neuroprotective in the context of cerebral ischemia." (PMID 35572539, 2022). "The regulatory effect of HG on macrophage polarization is supported by a previous study showed that HG significantly reduced M1 pro-inflammatory microglia and decreased the levels of TNF-α and IL-6 within the infarcted areas to alleviate cerebral ischemia/reperfusion injury [PMID: 32,848,779]." (PMID 35266443, 2022). "Elevated IL-6 levels also have been observed in cerebral ischemia." (PMID 35711345, 2022). "Its expression is affected in several of the major brain diseases, including cerebral ischemia, and animal models strongly suggest that IL-6 may play a role in the observed neuropathology and is therefore a clear target for therapies in cerebral ischemia." (PMID 36678774, 2022). "Therefore, restraining the abnormal activation of A1 astrocytes and production of TNF-α and IL-6 is conducive to alleviating neuronal damage after cerebral ischemia, which is also indispensable for functional rehabilitation." (PMID 35559267, 2022). "In addition, circulating miR-145 also increased significantly within 24 h of cerebral ischemia, and the level of circulating miR-145 was positively correlated with the increase in serum inflammatory factor IL-6." (PMID 33407066, 2021). "The results indicated that the inflammatory cytokines TNF‐α, TGF‐β, IL‐6, and IL‐1β were involved in the pathological injury process of cerebral ischemia, whereas casticin could significantly reduce their expression and the damage to brain cells." (PMID 33704926, 2021). "Therefore, the reduction of tissue IL-6 expression appears to be common upon beneficial intervention after cerebral ischemia." (PMID 34943061, 2021). "The value of IL-6 to predict mortality after cerebral ischemia has also been studied before." (PMID 33578805, 2021).
Cerebral ischemia (continued). "More and more studies have shown that a variety of inflammatory cytokines, such as TNF-α, IL-1β, and IL-6, are released after cerebral ischemia, which can transform ischemic injury into inflammatory injury and promote the apoptosis and necrosis of nerve cells and the formation of brain edema." (PMID 34447315, 2021). "In addition, D. moldavica has been reported to markedly improve on rat cerebral ischemia reperfusion injury by reducing the levels of IL-6, IL-8 and TNF-α and elevating the activities of superoxide dismutase (SOD) and glutathione peroxidase (GSH-Px)." (PMID 34960054, 2021). "Some studies have found that cytokines such as TNF-α, IL-1α/β and IL-6 affect phospholipid metabolism during acute inflammatory reaction under cerebral ischemia, producing arachidonic acid-like substances, ceramides and reactive oxygen species (ROS), which can cause damage to the brain tissue." (PMID 34504432, 2021). "Besides this, the inhibition of the Jak2/Stat3 pathway that can be activated with excess IL-6 during the acute phase of cerebral ischemia confers neuroprotection in ischemic stroke." (PMID 34943061, 2021). "In addition, IL-6 mRNA expression was elevated in a rat model of cerebral ischemia, and elevated IL-6 concentrations in the cerebrospinal fluid of patients with acute stroke was correlated with infarct volume." (PMID 34504432, 2021). "In the acute stage of cerebral ischemia, IL-6 would further aggravate ischemic injury." (PMID 34504432, 2021). "Rutaecarpine (MOL002662) can inhibit the production of pro-inflammatory factors IL6 and IL1B, thereby reducing the inflammatory response and oxidative stress caused by cerebral ischemia–reperfusion (CI/R) and increasing the levels of anti-inflammatory factors and superoxide dismutase." (PMID 33681222, 2021). "Brain ischemia stimulates IL-6 release in blood and in this way modulates HPA axis." (PMID 34955730, 2021). "However, studies have also shown that IL-6 is involved in the inflammatory response during cerebral ischemia." (PMID 32194375, 2020). "Furthermore, it has been revealed that IL‐6 is a key mediator in inflammatory responses to cerebral ischemia." (PMID 32583980, 2020). "It was reported that OXA pre-treatment could significantly downregulate the mRNA of TNFα and IL-6 in a model of cerebral ischemia, which meant the neuroinflammation was suppressed." (PMID 32539736, 2020). "Thus, the aim of this study was to evaluate the role of L-Ala-Gln to protect against brain ischemia-reperfusion injury in a gerbil model evaluated through immunohistochemistry (IHC) for the IL-6, TNF-α, NF-κB and HO-1." (PMID 32696813, 2020). "IL-6 plays a dual role in the inflammatory response induced by cerebral ischemia." (PMID 31164999, 2019). "Cerebral ischemia and reperfusion injury result from the rapid and explosive reoxygenation induced by the inflammatory response, which is tightly associated with inflammatory mediators such as IL-1β, TNF-α, and IL-6." (PMID 29867706, 2018). "In addition, many enriched inflammatory markers after cerebral ischemia, including interleukins IL-11 and IL-6, chemokines (Ccl4, Ccl2, Ccl5) and serum amyloid A (Saa3), were observed to be up-regulated consistent with reports elsewhere." (PMID 29896414, 2018). "To investigate whether adjudin-pretreated NSCs in the acute phase of cerebral ischemia had a better effect on immunomodulatory influence, we first examined IL-6, IL-1β, and TNF-α mRNA expression in both the cortex and the striatum." (PMID 29115993, 2017). "Some believed that IL-6 is beneficial in cerebral ischemia, but some deemed it may exacerbate brain injury." (PMID 28491108, 2017). "The present results suggest that Klotho may effectively inhibit RIG-I/IL-6-induced inflammation, likely through both NF-κB-dependent and -independent mechanisms that are involved in brain ischemia." (PMID 29403373, 2017). "The role of IL-6 in cerebral ischemia remains controversial." (PMID 27703487, 2016).
Cerebral ischemia (continued). "IL-6 expression was significantly increased in the acute phase of cerebral ischemia." (PMID 27586269, 2016). "The proinflammatory cytokine IL-6 contributes to regulation of Ca2+ influx in cerebral ischemia, but the role of IL-6 in regulating TRPM7 functioning is unknown." (PMID 27010689, 2016). "Within the first 24 hours of cerebral ischemia in animal models, inflammatory cytokines interleukin-1β (IL-1β), interleukin-6 (IL-6), and tumor necrosis factor-α are upregulated dramatically by up to 40- to 60-fold and are believed to affect the infarct volume and tissue damage." (PMID 24877133, 2014). "Furthermore, a study by Yamashita and coworkers showed that endogenous IL-6 plays a critical role in preventing apoptosis of damaged neurons in the acute phase of cerebral ischemia in mice." (PMID 23351591, 2013). "Evidence suggests that pro-inflammatory cytokines such as IL-1β, IL-6 and TNFα may influence the extent of neuronal damage after cerebral ischemia." (PMID 22873409, 2012). "Indeed, in our ischemic model we observed that cerebral ischemia-reperfusion increased IL-6 production significantly." (PMID 21957487, 2011). "Syringin reduces the expression of inflammatory factors(interleukin (IL)‐1β, tumor necrosis factor‐α, and IL‐6), and neutrophil infiltration and increases forkhead box O3A phosphorylation, thereby inhibiting nuclear factor kappa B expression and protecting against cerebral ischemia." (PMID 40566933, 2025). "Therefore, inhibiting the release of IL1β, IL6, and TNFα can effectively reduce neuron apoptosis, improve neurological deficits, reduce the disability rate and improve the quality of life of patients with cerebral ischemia." (PMID 41154631, 2025). "Considering that factors upregulated in the acute period after brain ischemia commonly result in a detrimental outcome (such as IL-6, IL-15), we wondered whether increased cerebral FGF21 expression during the subacute and delay phases could play a positive role." (PMID 40021824, 2025). "In studies investigating cerebral ischemia–reperfusion injury, fullerene C60 has been shown to reduce the development of cerebral edema and infarct area, decrease the neural defect development score, and significantly suppress interleukin 6 and matrix metalloproteinase 9 RNA expression." (PMID 39202513, 2024). "Thus, the increased IL-1β and IL-6 in the blood may contribute to the worsened neurological outcome with aging after brain ischemia." (PMID 37697393, 2023). "However, the mechanism(s) subserving the up-regulation of IL-6 during cerebral ischemia remains unclear." (PMID 35481263, 2022). "Moreover, silencing of MALAT1 drastically increased mRNA levels of pro-apoptotic factor Bim (a member of the Bcl-2 family) and induced pro-inflammatory cytokines, such as E-selectin, monocyte chemoattractant protein (MCP-1), and interleukin-6 (IL-6) after cerebral ischemia." (PMID 33236327, 2021). "Cerebral ischemia triggers inflammatory responses and numerous inflammatory mediators that exacerbate ischemic brain injury are induced at the transcriptional level, including enzymes required for prostaglandin synthesis, cytokines (e.g., IL-6 and TNF-α), and chemokines." (PMID 29234386, 2017). "Several cytokines, including TNFα, IL-1 beta, and IL-6 have been shown to participate in cerebral ischemia-induced inflammatory processes, but a complete database including all possible inflammatory mediators remains to be established in cerebral ischemia/reperfusion injury." (PMID 24204940, 2013). "Microglia and astrocytes are activated within minutes after cerebral ischemia and release some pro-inflammatory factors, such as TNF-α, NF-κB, IL-1β, and IL-6." (PMID 41329542, 2025). "Cerebral ischemia triggers diffusion impairment of the blood-brain barrier, concomitant with an accumulation of pro-inflammatory mediators (TNF-α, IL-1β, IL-6) within the brain and serum, provoking an inflammatory cascade." (PMID 40144659, 2025).
Cerebral ischemia (continued). "Activation of NF-κB induces the production of pro-inflammatory cytokines (IL-4, IL-10, IL-13, TGF-β) and adhesion molecules (IL-6, IL-1β and ICAM-1), thus intensifying tissue injury in cerebral ischemia-reperfusion." (PMID 40656619, 2025). "The cGAS/STING/IRF3 pathway mediates neuroinflammation during cerebral ischemia, where hyperactivation promotes excessive production of proinflammatory cytokines (e.g., TNF-α, IL-6) and chemokines, exacerbating cerebral damage." (PMID 41471264, 2025). "Brain ischemia induced significant elevations in plasma levels of the pro-inflammatory TNF-α, IL-6, and IL-1β, which were significantly mitigated by 3-MP." (PMID 40095189, 2025). "Following cerebral ischemia, inflammatory processes are initiated, with microglia and astrocytes releasing pro-inflammatory cytokines like IL-1β, TNF-α, and IL-6." (PMID 39625909, 2024). "In our experimental findings, we demonstrated the antioxidant and anti-inflammatory effects of skimmianine in rats subjected to cerebral ischemia/reperfusion injury, alongside the observed suppression of IBA-1, IL-6, and NF-κB protein levels." (PMID 39057078, 2024). "During cerebral ischemia, the expression of both pro-inflammatory, as TNF-α, IL-1β, IL-6, and anti-inflammatory cytokines, MCPIP1, rapidly increases throughout the brain tissue." (PMID 37812268, 2024). "Cerebral ischemia induced a transient increase of TNF, IL-1β, IL-6, CXCL1, and CCL5 at day 1 post-pMCAO, corresponding to the peak of pro-inflammatory cytokines typically observed in this model." (PMID 38142915, 2024). "In contrast to our results regarding pro-inflammatory cytokines in the circulation, we found that cerebral ischemia significantly up-regulated the expression of IL-1β, TNF-α, and IL-6 mRNA in cortical tissue." (PMID 38102677, 2023). "After cerebral ischemia, the NF-κB pathway extends the inflammatory response in the brain, activating inflammatory signals such as iNOS, COX-2, IL-1β, TNF-α, IL-6, and others." (PMID 35838888, 2023). "In the cerebral ischemia-reperfusion model used to study it, SYR, like other compounds, reduced the expression of NF-κB, IL-1β, IL-6, and TNF-α." (PMID 38813032, 2023). "HS treatment significantly decreased the levels of NF-κB, TNF-α, IL-6, MDA, and Caspase-3 and markedly demonstrated protection with respect to cerebral ischemia-reperfusion in rats." (PMID 37371417, 2023). "For example, cerebral ischemia and hypoxia can stimulate monocytes to yield inflammatory mediators: interleukin-6 (IL-6) and tumor necrosis factor (TNF), exacerbating cerebral ischemia and hypoxia, resulting in more extensive cerebral tissue destruction." (PMID 37616313, 2023). "Our real-time PCR and immunofluorescence results demonstrated that the propofol treatment decreased the expression level of IL-6 mRNA and the number of TLR4-expressing microglia after cerebral ischemia." (PMID 36117859, 2022). "Another study has proved that OH-F NPs can reduce the transcription of IL-6 and MMP-9 to protect BBB integrity and relieve brain edema after cerebral ischemia-reperfusion injury." (PMID 35480961, 2022). "The M1 type microglia excretes a large number of inflammatory factors such as IL-6, IL-1β, IL-12 and TNF-α, which aggravate cerebral ischemia/reperfusion injury." (PMID 35658867, 2022). "Middle cerebral artery occlusion (MCAO) wasperformed to establish a cerebral ischemia/reperfusion (I/R) model.Specific-pathogen-free male Sprague-Dawley rats were randomly divided into Sham,I/R, DEX, DEX+IL-6, and AG490 (a selective inhibitor of JAK2) groups." (PMID 35858000, 2022). "It has been seen that IL-6 and TNF-α increase significantly in cerebral ischemia and inhibiting the IL-6 and TNF-α pathways can alleviate cerebral ischemia injury." (PMID 36142849, 2022). "The ELISA results showed that the levels of IL-1β, IL-6, and TNF-α were abnormally increased in the serum of rats with cerebral ischemia." (PMID 35467483, 2022).